GLS (glutaminase)
Diseases named in the same sentence as GLS in open-access papers (continued):
Sharing a sentence is not in itself a finding about the gene and the disease.
cancer (continued). "In cytoplasm, glutamine is converted into glutamate by glutaminase isoenzymes (GLS-1 and GLS-2), which are differently expressed amongst cancer types, presenting an overlapped metabolic function and being pointed as relevant modulators of the clinical outcomes." (PMID 32993063, 2020). "Previous studies have described the opposing roles that GLS and GLS2 have in cancer." (PMID 31652551, 2019). "Moreover, the functional partners of GLS and GLS2 also eventually regulate the survival patterns of patients with certain types of cancer." (PMID 30871151, 2019). "In addition, a number of studies have argued that GLS and GLS2-mediated targeted therapies are promising molecular medicines that inhibit cancer development." (PMID 30871151, 2019). "An additional glutaminase inhibitor, compound 968, was shown to block oncogenic transformation in fibroblasts, while also reducing growth of cancer cells without affecting their normal counterparts." (PMID 31167399, 2019). "The chosen therapeutic strategy was based on the glutamine processing pathway in LUAD cells; wherein, we probed the ability of chemical inhibitors against glutaminase (CB‐839) and Psat1 (AOA) to modulate cancer cell growth by restricting the supply of α‐KG to the Krebs cycle." (PMID 31036704, 2019). "The normal prostatic epithelial cell RWPE-1 was barely affected after knockdown of GLS, suggesting that knockdown of GLS can inhibit cancer cells without markedly affecting normal cells." (PMID 31196962, 2019). "Glutaminase C (GAC), the first enzyme in glutaminolysis, has emerged as an important target for cancer therapy and many studies have focused on the mechanism of enhanced GAC expression in cancer cells." (PMID 29515166, 2018). "A number of drugs have been developed as glutaminase inhibitors; among these, BPTES (bis-2-(5-phenylacetamido-1,3,4-thiadiazol-2-yl)ethyl sulfide) is an important inhibitor that has been shown to be active in a variety of cancer cells." (PMID 29868609, 2018). "In the literature, glutaminase inhibition highlights possible negative effects of cancer progression by interrupting the glutamine-glutamate pathway." (PMID 29849950, 2018). "Besides targeting glutaminolysis outside the TCA cycle through GLS inhibition, several recent studies indicate that KGDHC represents a striking vulnerability for numerous cancers, and is a promising therapeutic target." (PMID 28748451, 2018). "In sum, our metabolic and transcriptomic analyses have revealed that depletion or inhibition of CDK4/6 in cancer cells leads to de novo addiction to MYC, and, as likely downstream consequences, also to glutaminase and mTOR signaling, as well as to a compromised adaptation to hypoxia." (PMID 28978620, 2017). "Importantly, we show that glutaminase inhibitors, 6-Diazo-5-oxo-L-norleucine (DON) or CB-839, hypersensitize cancer cells to alkylating agents both in vitro and in vivo." (PMID 29107960, 2017). "GLS1 shRNA (shGLS1), and the GLS-specific inhibitors bis-2-(5-phenylacetamido-1,3,4-thiadiazol-2-yl)ethyl sulfide (BPTES) and 968, reduce the growth of several cancer types in xenograft models." (PMID 26771232, 2016). "Furthermore, Myc-regulated Ldha, Pyruvate kinase M2 and Glutaminase have also emerged as promising targets based on experimental models of human cancer, suggesting that targeting various metabolic pathways regulated by Myc may prove beneficial in cancer therapies of patients." (PMID 22438825, 2012). "Transformed cells and cancer cells treated with 968 did not exhibit elevated basal glutaminase activity." (PMID 21234284, 2010). "Extracellular Gln depletion, pharmacological inhibition of glutaminase-1 (GLS1) in cancer cells, or Gln synthetase (GS) silencing in fibroblasts markedly impair senescent fibroblasts CM-induced invasion, EMT markers expression, and stemness features in cancer cells." (PMID 42121871, 2026).
cancer (continued). "Here, we observed that cisplatin‐resistant cancer cells are more sensitive to ASNase, and unlike the targeted ferroptosis inducers and glutaminase inhibitor, ASNase sensitivity was consistent between the cisplatin‐resistant models, although elevated in the glutamine‐dependent HCC4006 model." (PMID 40784667, 2025). "In summary, metabolic interventions—glutaminase blockade, PPP inhibition, PI3K/mTOR pathway suppression, and AMPK activation—exploit redox vulnerabilities generated by constitutive NRF2 activation, allowing invasive cancers to become more sensitive to oxidative stress and conventional therapy." (PMID 41470226, 2025). "Inhibition of glutaminase in MYC-driven RCC models has slowed tumor progression, indicating that targeting glutamine metabolism could be a viable therapeutic strategy for MYC-driven cancers." (PMID 40253354, 2025). "Glutamate is produced in mitochondria from glutamine, which is catalyzed by glutaminase (GLS), which is then converted into α-KG by glutamate dehydrogenase 1 (GDH1), fueling the TCA cycle and contributing to biosynthesis, energy generation and the cellular homeostasis of cancer cells." (PMID 39330272, 2024). "Since glutaminase isoform choice is an essential event in physiological and disease states and HuR is known as a bonafide RNA metabolism regulator, we hypothesized that HuR regulates GLS RNA metabolism in cancer." (PMID 38965208, 2024). "Moreover, bioinformatics tools identified interactions between cancer-related miRNAs miR-141-3p/miR-200a-3p and circRNA_100395, and target genes of the hsa_circRNA_100395/miR-141-3p/miR-200a-3p axis such as E2F3, CCND2, CCNG1, CDC25B, GLS, PTEN, and ZFPM2." (PMID 37511619, 2023). "Finally, the data on the gene expression profiles of cancer cell lines were integrated in the Genomics of Drug Sensitivity in Cancer (GDSC) database for drug sensitivity to fully explore the potential value of CDKN2A, DLAT, DLST, GLS, and PDHA1 genes as novel therapeutic targets." (PMID 36891150, 2023). "The conversion of glutamine to glutamate by glutaminase (GLS1 or GLS2), which is further transformed to α-ketoglutarate (α-KG) by glutamate dehydrogenase (GLUD1 or GLUD2) or aminotransferases, promotes the TCA metabolism that contributes to sustaining the energy used for cancer cell proliferation." (PMID 35054324, 2022). "Phenylacetate inhibits cancer cell proliferation by reducing Gln availability in the blood, while Bis-2-5-phenylacetamido-1,3,4-thiadiazol-2-ylethyl sulfide (BPTES), an inhibitor of the glutaminase—the rate-limiting step in Gln catabolism—blocked the growth of xenografts." (PMID 35367410, 2022). "In endocrine-related cancers, cancer cells uptake glutamine via ASCT2; intracellular glutamine can be utilized first by converting to glutamate catalyzed by mitochondrial enzyme GLS, and then glutamate is further catabolized to TCA cycle substrate α-KG, either via GLUD or transaminase." (PMID 36077501, 2022). "Recent data demonstrate that L-asparaginase activity alone may not be sufficient for L-ASNase cytotoxicity, and that glutaminase activity may be required for full antitumor efficacy against cancer." (PMID 34948436, 2021). "Moreover, the biosynthesis of serine and glycine affects cellular antioxidative capability and also promotes tumor growth; The c-MYC oncogene activates the expression of glutaminase (GLS1/GLS2) and glutamine metabolism in cancer cells, and glutamine can be converted to glutamate even in hypoxia." (PMID 33849550, 2021). "Therefore, many cancer cell types depend heavily on the elevated glutaminolysis, which converts glutamine into TCA cycle metabolites in a metabolic pathway that involves the initial deamination of glutamine by GLS, the most important enzyme in glutaminolysis." (PMID 33513833, 2021).
cancer (continued). "The conversion of Gln to ketoglutarate, a tricarboxylic acid cycle intermediate, via glutaminase and alanine aminotransferase, is critical for tumor development, and thus targeted therapy by selective inhibition of GLS is a novel strategy of considerable interest for the treatment of cancer." (PMID 35223460, 2021). "Our study demonstrated that in most cancer types, SLC1A5, SLC7A5, SLC7A11, and SLC3A2 were highly expressed and indicative of poorer survival outcomes, while the effects of changes in the expression of GLS2 and GLS depended on the type of cancer under consideration." (PMID 34573287, 2021). "Interestingly, a completely different response is found for cancer cells grown in the absence of Gln or after silencing/inhibition of GLS isoform: cells enter the S phase but fail to progress into G2/M49,50." (PMID 32042057, 2020). "GLS is not the only marker associated with glutamine metabolism; the glutamine transporter ASCT2 (SLC1A5) is actively investigated as a possible therapeutic target to block cancer cell growth and development." (PMID 32974128, 2020). "There are two strategies for targeting glutamine metabolism in cancer cells: inhibition of glutaminase that can convert glutamine into glutamate and blockage of the major glutamine transporter alanine-serine-cysteine transporter 2 (ASCT2) to suppress the influx of glutamine into the cancer cells." (PMID 32509584, 2020). "Thus, two cancer cell models with increased GLS2 expression and nuclear accrual showed a stabilization of the cell cycle in the G2/M phase, in sharp contrast with GLS isoforms whose expression was upregulated in G1 and S phases in association with cell proliferation." (PMID 32042057, 2020). "ASNase could break down both asparagine and glutamine, even though its glutaminase activity was not required for ASNS‐negative cancer cells." (PMID 31523835, 2019). "Moreover, expression of combined GLS and GLS2-centered-signature-gene set might regulate the clinical outcomes in certain cancer." (PMID 30871151, 2019). "Notably, ASNase has a dual asparagine and glutamine deaminase activity; however, its glutaminase activity was not required for anticancer effect in asparagine synthetase (ASNS)‐negative cancer cells." (PMID 31523835, 2019). "CA and Met are absorbed and metabolized by cancer cells and are not toxic to normal cells However, our data show that Met may to a small extent reverse CA-dependent GLS inhibition in C4-I cell line." (PMID 29958416, 2018). "Interestingly, inhibitors of GLS are being explored: BPTES and CB839 have been shown to induce apoptosis in cancer cells." (PMID 28446878, 2017). "The glutaminase activity of L-asparaginase is not required for anti-cancer activity against ASNS-negative cancer cells, therefore there have been attempt for purifying glutaminase-free L-asparaginase from other sources or engineering L-asparaginase to be glutaminase-free." (PMID 28750681, 2017). "However, when these same cancer cells grow as tumors in animals, they process less glutamine and are not affected by glutaminase inhibitors." (PMID 28826492, 2017). "Interestingly, the glutaminase inhibitor treatment failed to sensitize cancer cells to other DNA damaging agents, such as Doxo or CPT, indicating that inhibition of glutamine metabolism only affects methylation damage repairs, but not DSB repairs." (PMID 29107960, 2017). "Additionally, glutaminase inhibition could be more broadly applicable in a variety of cancer types when combined with a small molecule activator of NRF2, which renders KEAP1 wild type cells highly sensitive to glutaminase inhibition." (PMID 28967864, 2017). "The effect of ENO1 silencing opens new possibilities for cancer treatment, based on a combination between ENO1 targeting and therapies that are able to increase oxidative and metabolic stress, such as chemotherapy and radiation, or glutaminase and oxidative phosphorylation inhibitors, respectively." (PMID 26734996, 2016).
cancer (continued). "Another glutaminase inhibitor, bis-2-[5-(phenylacetamido)-1,3,4-thiadiazol-2-yl]ethyl sulfide (BPTES), and its analogs significantly diminish growth of tumor xenografts in vivo and proliferation of cancer cells in vitro for several tumor types, including lymphomas, breast cancers, and gliomas." (PMID 26139106, 2015). "Glutaminase inhibition blocks the conversion of glutamine to glutamate and thus disables the conversion of glutamate into α-ketoglutarate by glutamate dehydrogenase, which normally enters the TCA cycle to provide energy and bio-precursors for cancer cell growth." (PMID 25026281, 2014). "Moreover, glutaminase activity is markedly increased in different transformed fibroblasts and in other cancer cells compared to their non-transformed counterparts, in the absence of any apparent changes in the expression levels of the enzyme." (PMID 21234284, 2010). "An even more compelling indication that basal glutaminase activity is increased in transformed/cancer cells, independent of changes in the expression levels of the enzyme, comes from experiments where we ectopically expressed GAC in Dbl-transformed cells and normal fibroblasts." (PMID 21234284, 2010). "However, GLS inhibitors have not progressed to the clinical stage due to lack of efficacy, highlighting the need for innovative approaches to advance the field of metabolic inhibition in cancer therapy." (PMID 38790264, 2024). "However, some studies have found that inhibiting GLS does not always bring about desired results, especially in cancers with poor vascularization and limited ability of extracting circulating Gln, where they depend on the increased expression of GS to synthesize de novo Gln autonomously." (PMID 34054545, 2021). "Furthermore, the existence of an alternative pathway connecting glutamine and mTORC1 might explain the lack of efficacy of targeting GLS as a potential strategy against cancer." (PMID 34376668, 2021). "However, to date, there are no glutaminase inhibitors approved for usage in cancer treatment." (PMID 30186229, 2018). "In addition, glutaminase inhibitor treatment, by indirectly inhibiting the ALKBH enzymes, may serve as an effective strategy to block the oncogenic function of ALKBH enzymes and restore cancer cell sensitivity to alkylating agents." (PMID 29107960, 2017). "In addition, inhibitors of glutaminase were more efficient in MAPK-inhibitor-resistant cells with regard to decreased cell survival indicating that besides glucose metabolism, glutamine metabolism may be a suitable therapeutic target in cancer cells." (PMID 28724379, 2017). "By comparing the lists of top-ranking cancer-related target genes, we were able to identify seven promising cancer-related genes that may be targets of the hsa_circRNA_100395/miR-141-3p/ miR-200a-3p axis in PTC (in order of descending rank): E2F3, GLS, CCND2, PTEN, CCNG1, CDC25B, and ZFPM2." (PMID 28288173, 2017). "Telaglenastat is inhibitor of glutaminase 1 (GLS1), which emerges as an essential non-glucose source and TCA fuel to refill TCA cycle intermediates, especially in cancer cells under needs or stress." (PMID 41331927, 2025). "The dual inhibitor of GLS and GDH, CPD‐3B (Hexylselen) has demonstrated to effectively disrupt mitochondrial membrane potential and to induce apoptosis of glutamine addicted cancer cells without showing toxicity to normal cells." (PMID 38105543, 2025). "Interestingly, a small molecule inhibitor of glutaminase (GLS), CB-839, has been shown to inhibit growth of TNBC xenografts as a single agent and in combination with paclitaxel, and therefore, CB-839 may be an effective as a part of a combination anti-cancer therapy for TNBC cases in the clinic." (PMID 28696357, 2017). "The need for a dual GLS and ASNS inhibition could explain the lack of effectivity of targeting only glutaminolysis as a therapeutic approach against cancer." (PMID 34376668, 2021).
cancer (continued). "Among these, the compound CB-839 is a noncompetitive GLS inhibitor able to inhibit the entry of substrates into the TCA cycle, thus reducing cell viability and cancer stemness, increasing chemosensitivity, and inducing apoptotic cell death in several cancer types." (PMID 32825551, 2020). "Unlike GLS, which is active in several types of cancer and is indirectly promoted by c-myc through repressing the expression of miR-23a/b, the role of GLS2 in cancer seems more complex." (PMID 28811348, 2017).